MIR1260B (microRNA 1260b)
Synonyms: hsa-mir-1260b; mir-1260b
Gene: MicroRNA gene on chromosome 11 (96,341,438 to 96,341,526, forward strand). Ensembl gene ENSG00000266192.
Homologues: Orthologues: chimpanzee MIR1260B (100% identical).